ADAR (adenosine deaminase RNA specific)
Description:
Catalyzes the hydrolytic deamination of adenosine to inosine in double-stranded RNA (dsRNA) referred to as A-to-I RNA editing. This may affect gene expression and function in a number of ways that include mRNA translation by changing codons and hence the amino acid sequence of proteins since the translational machinery read the inosine as a guanosine; pre-mRNA splicing by altering splice site recognition sequences; RNA stability by changing sequences involved in nuclease recognition; genetic stability in the case of RNA virus genomes by changing sequences during viral RNA replication; and RNA structure-dependent activities such as microRNA production or targeting or protein-RNA interactions. Can edit both viral and cellular RNAs and can edit RNAs at multiple sites (hyper-editing) or at specific sites (site-specific editing). Its cellular RNA substrates include: bladder cancer-associated protein (BLCAP), neurotransmitter receptors for glutamate (GRIA2) and serotonin (HTR2C) and GABA receptor (GABRA3). Site-specific RNA editing of transcripts encoding these proteins results in amino acid substitutions which consequently alters their functional activities. Exhibits low-level editing at the GRIA2 Q/R site, but edits efficiently at the R/G site and HOTSPOT1. Its viral RNA substrates include: hepatitis C virus (HCV), vesicular stomatitis virus (VSV), measles virus (MV), hepatitis delta virus (HDV), and human immunodeficiency virus type 1 (HIV-1). Exhibits either a proviral (HDV, MV, VSV and HIV-1) or an antiviral effect (HCV) and this can be editing-dependent (HDV and HCV), editing-independent (VSV and MV) or both (HIV-1). Impairs HCV replication via RNA editing at multiple sites. Enhances the replication of MV, VSV and HIV-1 through an editing-independent mechanism via suppression of EIF2AK2/PKR activation and function. Stimulates both the release and infectivity of HIV-1 viral particles by an editing-dependent mechanism where it associates with viral RNAs and edits adenosines in the 5'UTR and the Rev and Tat coding sequence. Can enhance viral replication of HDV via A-to-I editing at a site designated as amber/W, thereby changing an UAG amber stop codon to an UIG tryptophan (W) codon that permits synthesis of the large delta antigen (L-HDAg) which has a key role in the assembly of viral particles. However, high levels of ADAR1 inhibit HDV replication.
Synonyms: DRADA; p136; IFI-4; ADAR1; DSRAD; G1P1; IFI4; AGS6; DSH; K88DSRBP
Tractability: PROTAC: UniProt records ubiquitination sites on it; ubiquitination databases record sites on it; its protein half-life has been measured.
Target class: Enzyme; Hydrolase
Gene: Protein-coding gene on chromosome 1 (154,581,695 to 154,628,013, reverse strand). Ensembl gene ENSG00000160710.
Subcellular location: Cytoplasm (Isoform 1); Nucleus; Cytoplasm (Isoform 5); Nucleus, nucleolus
Subcellular location (Human Protein Atlas): Nucleoli; Nucleoplasm
Pathways (Reactome):
Immune System: Interferon alpha/beta signaling; PKR-mediated signaling
Metabolism of RNA: C6 deamination of adenosine; Formation of editosomes by ADAR proteins
Gene Ontology:
Molecular function: double-stranded RNA adenosine deaminase activity; protein binding; RNA binding; double-stranded RNA binding; adenosine deaminase activity
Biological process: adenosine to inosine editing; base conversion or substitution editing; mRNA modification; positive regulation of viral genome replication; pre-miRNA processing; response to interferon-alpha; response to virus; RISC complex assembly; innate immune response; cellular response to virus; RNA processing
Cellular component: cytoplasm; membrane; mitochondrion; nucleolus; nucleoplasm; nucleus; supraspliceosomal complex; cytosol; nuclear lumen
Genetic constraint (gnomAD): Loss-of-function variants: 41 observed, 118.57 expected, observed/expected ratio (o/e) 0.35, 90% interval 0.27 to 0.45. The upper end of that interval is the gene's LOEUF score, 0.45, which puts it in group 1 of 6, group 1 being the genes least tolerant of losing a copy. Missense variants: 1,242 observed, 1,618.8 expected, observed/expected ratio (o/e) 0.77, 90% interval 0.73 to 0.8. Synonymous variants: 605 observed, 603.63 expected, observed/expected ratio (o/e) 1, 90% interval 0.94 to 1.07.
Gene-disease validity (ClinGen):
ClinGen rates the evidence that ADAR causes each of these diseases.
ADAR-related type 1 interferonopathy (autosomal dominant; autosomal recessive): Definitive. Any type 1 interferonopathies in which the cause of the disease is a variation in the ADAR gene.
Leigh syndrome (autosomal recessive): Limited. A progressive neurological disease defined by specific neuropathological features associating brainstem and basal ganglia lesions.
Homologues: Orthologues: chimpanzee ADAR (99% identical), macaque ADAR (96% identical), pig ADAR (82% identical), rabbit ADAR (81% identical), guinea pig ADAR (79% identical), rat Adar (76% identical), mouse Adar (74% identical), dog ADAR (68% identical), zebrafish adar (43% identical), tropical clawed frog adar (40% identical), Caenorhabditis elegans adr-2 (13% identical), Drosophila melanogaster blanks (5% identical), and 1 more. Paralogues in human: ADARB2 (19% identical), ADARB1 (17% identical), ADAD1 (11% identical), ADAD2 (11% identical), ADAT1 (11% identical), ZFR2 (9% identical), ZFR (8% identical), STAU2 (8% identical), STAU1 (8% identical), TARBP2 (7% identical), PRKRA (6% identical), STRBP (6% identical), and 2 more.
Diseases named in the same sentence as ADAR in open-access papers:
ADAR is named in the same sentence as 266 diseases in open-access papers, as found by Europe PMC text mining. Sharing a sentence is not in itself a finding about the gene and the disease. The quoted sentences say what the papers report.
Aicardi-Goutières syndrome (93 papers, 2013 to 2026). "In humans, ADAR loss-of-function mutations and a dominant negative mutation cause Aicardi–Goutières syndrome (AGS)." (PMID 39030076, 2025). "It is known that biallelic pathogenic variants in ADAR that reduce its editing activity result in excessive release of interferons (IFNs) and tissue damage, and present as Aicardi Goutieres syndrome." (PMID 40215316, 2025). "Heterozygous pathogenic variants in ADAR have been associated with dyschromatosis symmetrica hereditaria, while biallelic pathogenic variants have been associated with Aicardi-Goutières syndrome 6 (AGS6)." (PMID 40755772, 2025). "Approximately 7% of Aicardi-Goutières Syndrome cases are caused by pathogenic variants in the ADAR gene and are classified as Aicardi-Goutières Syndrome type 6." (PMID 39732715, 2024). "Loss-of-function mutations in ADAR are associated with rare autoinflammatory disorders including Aicardi–Goutières syndrome (AGS), defined by a constitutive systemic up-regulation of type I interferon (IFN)." (PMID 37290963, 2023). "Mutations in ADAR can be observed in many autoimmune diseases, such as Aicardi-Goutières syndrome (AGS)." (PMID 37915585, 2023). "Dominant-negative mutations in the ADAR gene lead to Aicardi-Goutières syndrome, an inherited encephalopathy characterized by severe neurological dysfunctions and psychomotor retardation." (PMID 35216494, 2022). "Conversely, mutations in ADAR, the gene encoding ADAR1, are associated with immune diseases, like Aicardi-Goutières syndrome (AGS), as a consequence of Type I Interferon hyperactivation." (PMID 35757716, 2022). "One form of Aicardi-Goutières Syndrome is caused by an inactivating mutation in ADAR, the gene that encodes adenosine deaminase specific for double-stranded RNA (dsRNA), ADAR, responsible for deaminating adenosines in dsRNAs to inosine, termed A-to-I editing." (PMID 33969287, 2021). "In Aicardi-Goutières Syndrome, loss of ADAR function results in accumulation of endogenous dsRNAs, activation of dsRNA sensors, and induction of IFNI/III, ISGs, additional inflammatory mediators and death in both murine models and human syndromes." (PMID 33969287, 2021). "Reduced A-to-I editing of endogenous double-stranded RNAs (dsRNAs), as a result of inactivating mutations in ADAR, produces one form of Aicardi-Goutières Syndrome, with an immune response similar to an anti-viral response." (PMID 33969287, 2021). "ADAR heterozygous mutations are been found in dyschromatosis symmetrica hereditaria and homozygous or compound heterozygous variations in Aicardi-Goutières syndrome." (PMID 32641076, 2020). "Of note, mutations in ADAR genes were linked to Aicardi-Goutières syndrome (AGS), a diseases which is associated with increased levels of IFN-α." (PMID 30699960, 2019). "Loss-of-function mutations in ADAR p150 allow persistent activation of the interferon system by Alu dsRNAs and are causal for Aicardi-Goutières Syndrome." (PMID 30729177, 2019). "Such presentation bears some resemblance to Aicardi-Goutières syndrome associated with mutations in ADAR." (PMID 30406060, 2018). "Deficiency of ADAR causes Aicardi-Goutières syndrome characterized by childhood-onset encephalopathy and overproduction of type-I interferons." (PMID 30406060, 2018). "The importance of the immune-dampening effect of ADAR-p150 is demonstrated in loss-of-function mutations, which result in Aicardi Goutieres syndrome, an infantile inflammatory encephalopathy that can also cause striatal necrosis, a brain structure implicated in PD." (PMID 40215316, 2025). "Therefore, we isolated fibroblasts from patients with Aicardi-Goutières syndrome (AGS) (mutation in adenosine deaminases acting on RNA (ADAR)) and STING-associated vasculopathy with onset in infancy (SAVI)/chilblain lupus (mutation in STING)." (PMID 39707025, 2025). "Interestingly, ADAR mutations drive PKR-linked immune diseases such as the Aicardi-Goutières syndrome." (PMID 38932237, 2024).
Aicardi-Goutières syndrome (continued). "Moreover, loss of function mutations in ADAR genes are linked to an inherited infantile encephalopathy known as Aicardi-Goutières syndrome (AGS)." (PMID 35771000, 2022). "A likely pathogenic nonsynonymous variant rs145588689 (c.577C>G: p.P193A) in the ADAR gene associated with Aicardi-Goutières syndrome (AGS) was found to be segregated with disease in compound heterozygous state in 22 out of 23 unrelated families as well as in multiple unrelated AGS patients." (PMID 34905135, 2021). "Heterozygous pathogenic variants in ADAR have been associated with dyschromatosis symmetrica hereditaria (DSH) and biallelic pathogenic variants have been associated with Aicardi-Goutières syndrome 6 (AGS6)." (PMID 40755772, 2025). "A subset of Aicardi–Goutières syndrome (AGS), a severe pediatric autoinflammatory disease and type I interferonopathy, are caused by inherited ADAR mutations." (PMID 37290963, 2023). "A total of 4 and 2 individuals were carriers for a causal variant in the ADAR and NLRP12 gene causative for Aicardi-Goutières syndrome (AGS) and familial cold autoinflammatory syndrome (FACS)." (PMID 34905135, 2021). "In order to avoid MDA5-driven immunopathologies (e.g., Aicardi-Goutières syndrome), cells use adenosine deaminases acting on RNA (ADAR) to perform adenosine-to-inosine RNA editing and prevent the formation of RNA duplexes." (PMID 31076589, 2019). "The imbalance of ADAR expression or activity may lead to a variety of diseases, such as cancer, Aicardi–Goutières syndrome, and amyotrophic lateral sclerosis." (PMID 36999050, 2023). "Certainly in the autoimmune vasculitis variants known as Aicardi-Goutières syndrome, where altered degradation of cytosolic DNA or RNA is caused by mutations in TREX1/SAMHD1/RNASEH2A/B/C/ADAR/IFIH1/PNPT1, the progressive immune activation leads to phenotypes of neuro-inflammation/-degeneration." (PMID 34345994, 2021). "Activation of the innate immune sensing system, termed an interferonopathy, is observed in the subset of Aicardi-Goutières syndrome (AGS) patients who harbor mutations in ADAR, demonstrating that the transcriptional response to loss of ADAR1 activity is conserved across mammals." (PMID 28874170, 2017). "The genetic dissection of a particular type I interferonopathy, Aicardi-Goutières syndrome, initially described as an early-onset progressive brain disease, identified mutations of the TREX1, RNASEH2A, RNASEH2B, RNASEH2C, SAMHD1, ADAR, and MDA5 genes as causal." (PMID 27190218, 2016).
viral infection (87 papers, 2007 to 2026). "RNA-editing enzyme families in host cells, such as APOBEC and ADAR, are able to induce point mutations to suppress viral infection." (PMID 36851535, 2023). "AIDD-based results show importance of diversity of ADAR isoforms, key RNA editing enzymes linked with the innate immune system and viral infections." (PMID 33375933, 2020). "Currently, mutations or changes in expression induced disorder of ADAR activity have been linked to a variety of human diseases, ranging from neurological and neurodegenerative diseases, metabolic diseases, viral infections, autoimmune disorders to cancers." (PMID 30524204, 2018). "ADAR-1 is linked to both miRNA biogenesis and virus infection." (PMID 33984068, 2021). "Recently, several studies discovered more functions of ADAR, including RNA editing in viral infection and the response to cellular stress factors." (PMID 39641903, 2025). "ADAR proteins play a pivotal role in the innate immune response to viral infections, where editing can have a range of pro- or antiviral effects and can contribute to viral evolution." (PMID 39066279, 2024). "ADAR-mediated RNA editing is a crucial mechanism in human cells that plays a key role in fighting against viral infections." (PMID 38203521, 2023). "During different stages of viral infection, ADAR exhibits different proviral and antiviral effects that depend on the inflammatory response." (PMID 37915585, 2023). "Secondly, understanding how ADAR rapidly responds to viral infections, how host cells dynamically regulate the concentration of ADAR, and how this “double-edged sword” affects the diverse impact on dsRNAs are crucial for drug design." (PMID 37915585, 2023). "ADAR1 is the most commonly studied ADAR protein in viral infections and can be divided into two subtypes, ADAR1p150 and ADAR1p110." (PMID 36550502, 2022). "Answering these questions will be essential to developing our understanding of the relationship between ADAR editing and viral infection." (PMID 34694399, 2021). "ADAR editing is important for regulating neural functions and autoimmunity, and has a key role in the innate immune response to viral infections, where editing can have a range of pro- or antiviral effects and can contribute to viral evolution." (PMID 34694399, 2021). "Although the details of links between changes in ADAR editing patterns due to viral infections and subsequent short- or long-term neurological consequences remain to be elucidated, available evidence points to their existence across multiple studies." (PMID 34694399, 2021). "In a mouse model of viral infection that recapitulates ASD-associated behavioral changes, ADAR activity is increased, possibly due to IFN-induced ADAR expression." (PMID 34916907, 2021). "There is a debate today surrounding the role of ADAR in viral infections: in some case it was found to be pro-viral whereas in other cases it has been shown to be anti-viral." (PMID 33147296, 2020). "We analyzed the expression profiles of the four C. gigas ADAR genes in available RNA-seq samples obtained from oyster naïve tissues, developmental stages, abiotic stimuli, bacterial challenges, and viral infections." (PMID 31337330, 2019). "Although an IFN homolog has not yet been identified in bivalves, several ISG homologs such as viperin, 2′-5′-oligoadenylate synthase and double-stranded RNA-specific adenosine deaminase (ADAR) have been reported as upregulated upon viral infection." (PMID 31337330, 2019). "Recently, there was a controversy for the roles of ADAR enzymes during viral infection, and different lines of evidences indicated ADAR enzymes can play both antiviral role and also act as pro-viral proteins." (PMID 29363430, 2018). "Driver genes of this sub-network (OAS2, ISG15, STAT1, and ADAR) are involved in immune response to viral infections, and expression of these genes is inducible by interferon." (PMID 25868721, 2015).